RNU6-1300P (RNA, U6 small nuclear 1300, pseudogene)
Gene: Small nuclear RNA gene on chromosome 8 (74,048,677 to 74,048,784, forward strand). Ensembl gene ENSG00000212348.
Homologues: Orthologues: chimpanzee U6 (97% identical), macaque U6 (86% identical), mouse Gm23318 (65% identical), mouse Gm25054 (56% identical), rat LOC120095371 (56% identical). Paralogues in human: RNU6-43P (83% identical), RNU6-11P (81% identical), RNU6-140P (81% identical), RNU6-25P (81% identical), RNU6-33P (81% identical), RNU6-37P (81% identical), RNU6-454P (81% identical), RNU6-7 (81% identical), RNU6-8 (81% identical), RNU6-1 (81% identical), RNU6-1020P (81% identical), RNU6-1331P (81% identical), and 1287 more.